TTK (TTK protein kinase)
Diseases named in the same sentence as TTK in open-access papers (continued):
Sharing a sentence is not in itself a finding about the gene and the disease.
cancer (continued). "Expression of CCNB1 is significantly elevated in samples from LUAD patients and is associated with advanced tumor stage and shorter OS, and TTK is a mitotic checkpoint kinase that is present in higher amounts in some human cancers than in normal tissue." (PMID 35860256, 2022). "A recent review reported that high TTK expression is commonly found in many types of human malignant tumors." (PMID 35784389, 2022). "The LASSO model showed that TTK, ANLN, AIM1L and person neoplasm cancer status should be underlying candidates of OS in HCC." (PMID 34130591, 2021). "Problem 1 asked teams to predict molecules that bound the RETM955T-associated cancer targets RET[M918T], BRAF, SRC, S6K, and avoided binding to MKNK1, TTK, ERK8, PDK1, and PAK3." (PMID 34520464, 2021). "MPS1 or TTK protein controls the mitotic phase of the cell cycle and is highly expressed in various cancers including bile duct, colon, liver, and lung cancers." (PMID 33450849, 2021). "Targeting TTK is a promising strategy for cancer treatment, and several TTK inhibitors are being tested in pre-clinical studies and clinical trials." (PMID 34516342, 2021). "Among the stemness-related genes, TTK was the cancer driver gene with a significant driver level according to the OncoVar database." (PMID 34178686, 2021). "It is noteworthy, however, that RNF128, SLC16A1, SPRED1, TNRC6B, and TTK are novel in that they are found only among the candidate cancer genes identified by forward genetic screens in mice or among the genes whose expression changes in cancer." (PMID 33427197, 2021). "TTK has been reported to regulate the progression of several cancer such as hepatocellular carcinoma, lung cancer, and glioma." (PMID 34516342, 2021). "There exist a positive correlation between EZH2 and the five genes (CHEK1, MAD2L1, RFWD3, TRAIP, and TTK) in the majority of detailed cancer types as shown in the form of heatmap data." (PMID 34381492, 2021). "Upregulation of TTK, NEK2, and CDK1 was associated with growth factor-initiated signaling, i.e., salvage pyrimidine and purine pathways are frequently deregulated in cancer." (PMID 34072728, 2021). "We demonstrate that genes identified in this study and their inhibitors (such as TTK inhibitor used in this study) have the potential to inhibit/reduce genomic instability and growth of cancer cells in vitro and in vivo." (PMID 34031527, 2021). "TTK is a dual-specificity protein kinase, and the dysregulated expression of this protein has shown to be involved in cell proliferation in multiple cancers." (PMID 33829064, 2021). "TTK is a regulator of spindle assembly checkpoint signaling, playing an important role in cell cycle control and tumorigenesis in various cancers." (PMID 34876569, 2021). "After adjusting person neoplasm cancer status, ANLN and TTK levels in Cox model, AIM1L was identified as a risk factor for predicting OS in HCC patients (HR = 1.5, P = 0.037)." (PMID 34130591, 2021). "IHC staining revealed a higher positive rate of TTK in OC tissues (25/32, 78.1%) compared with normal tissues adjacent to cancer (6/32, 18.8%), suggesting that the expression level of TTK protein was also up-regulated in the tumorigenesis of OC." (PMID 34516342, 2021). "In these two matched pairs of human specimens, high levels of TTK have been found in cancer parts comparing with normal parts at mRNA level as determined by NGS." (PMID 32121246, 2020). "Mechanistically, TTK exerted a significant enhancement in cancer growth by neurotensin (NTS) upregulation, and subsequently increased the expression of cyclin A and cdk2, which was resulting in the increase of DNA synthesis." (PMID 32121246, 2020). "Elevated TTK level facilitates chromosome instability and aneuploidy, thus contributing to cancer cell proliferation and invasion." (PMID 32514252, 2020). "Previous studies have revealed that TTK is highly expressed in several malignant tumors, and its increased expression indicates a poor prognosis." (PMID 33061942, 2020).
cancer (continued). "Consistently, the cell cycle analysis revealed the S-phase population was decreased (from 19.45% to 12.37%) in TTK knockdown cancer cells which is consistent with BrdU incorporation analysis." (PMID 32121246, 2020). "TTK (Thr/Tyr kinase), a dual serine/threonine kinase, is considered to act as a cancer promoter by controlling SAC." (PMID 32121246, 2020). "Previous studies have shown that TTK is often overexpressed in many cancers and that the upregulation of TTK is correlated with poor survival." (PMID 32462022, 2020). "Clinical datasets and cancer genomic datasets from the cBioPortal website were analysed, and the results showed that in cases with TTK, CDC25A, and ESPL1 amplification, EC patients had worse survival outcomes." (PMID 33282948, 2020). "TTK is expressed at relatively high levels in testis, thymus tissues and various malignant tumor tissues, but is not detected in most other benign tissues." (PMID 30656409, 2019). "Among all tumor-associated antigens, cancer–testis antigens such as MAGE-A, NY-ESO-1, LAGE-1, and TTK are of particular concern as a potential target for immunotherapy by reason of their strong in vivo immunogenicity and unique expression patterns." (PMID 30656409, 2019). "In many studies of ESCC antigens expression, the expression of TTK was observed as a key indicator for observing the clinical response of patients to cancer vaccination at present, and also as TTK inhibitors for ESCC patients in the future." (PMID 30656409, 2019). "Previous studies characterized the role of TTK in mitotic regulation, and overexpression of TTK facilitates genomic instability in cancer." (PMID 30206215, 2018). "Cell proliferation in other cancer lines is also inhibited by treatment with a targeted TTK inhibitor, NMS-P71527, although TNBC cellular response to NMS-P715 has not been tested." (PMID 30206215, 2018). "The oncogenic function of TTK has been well demonstrated, and TTK inhibitors have been used to treat cancers." (PMID 30038707, 2018). "The list of identified TTK phosphorylation substrates remain sparse and the key substrates for TTK-dependent cancer growth remain unestablished." (PMID 28380042, 2017). "Secondly, whereas TTK is highly expressed in several cancer types, the relationship between expression level and severity of disease is complex and contradictive." (PMID 28415765, 2017). "Several different TTK inhibitors have been tested in mouse xenograft models of human cancer cell lines and shown to be efficacious." (PMID 28415765, 2017). "Previous studies have investigated the role of TTK in cancer using pharmacologic inhibitors in cancer cell lines." (PMID 28380042, 2017). "Several TTK inhibitors have been shown to reduce the growth of xenografts of human cancer cell lines from diverse tumor tissue origin in mice." (PMID 28415765, 2017). "It has been suggested that TTK inhibitor therapy would be in particular effective in cancers characterized by highly unstable genomes." (PMID 28415765, 2017). "Therapeutic approaches that inhibit TTK would likely target cancer cells only, circumventing unwanted off-target effects." (PMID 27618777, 2016). "Regardless of the tumor differentiation grade, elevation of expressed TTK protein was clearly noted in cancer tissues." (PMID 27618777, 2016). "Considering the anchorage-independent growth ability of cancer cells, it indicates the role of TTK for increasing HCC cell aggressiveness." (PMID 26418879, 2015). "In particular, it has been demonstrated that TTK protein kinase (TTK), up-regulated lung cancer 10 (URLC10) and insulin-like growth factor–II mRNA binding protein 3 (KOC1) are promising targets for cancer vaccination in advanced ESCC patients." (PMID 24708624, 2014). "The peptide vaccine included the 5 peptides as follows; TTK protein kinase (TTK), up-regulated lung cancer 10 (URLC10), insulin-like growth factor–II mRNA binding protein 3 (KOC1), vascular endothelial growth factor receptor 1 (VEGFR1) and 2 (VEGFR2)." (PMID 24708624, 2014).
cancer (continued). "Our results are consistent with previous reports showing that TTK depletion reduces cell viability in a large variety of cancer cell lines." (PMID 23700430, 2013). "TTK protein kinase (TTK), a serine/threonine kinase, has been implicated in the progression of various cancers, but its role in BC has not been fully elucidated." (PMID 40269198, 2025). "The combined treatment of a TTK inhibitor with a CDK2 antagonist might eradicate persistent cancer cells that follow single-agent CDK2 inhibitor treatment as reported in this study." (PMID 40232858, 2025). "Especially, TTK has previously been described as a promising target for cancer treatment." (PMID 40165380, 2025). "High TTK and low MCPH1 protein expression was significantly correlated, highlighting TTK's potential as a biomarker for BC and a therapeutic target for MCPH1‐deficient cancer cells." (PMID 39775836, 2025). "Elevated TTK expression may also enhance the proliferation and invasiveness of cancer cells, facilitating their spread to regional lymph nodes." (PMID 39775836, 2025). "Additionally, TTK was overexpressed in various types of solid tumors, underscoring its significance in cancer progression." (PMID 40269198, 2025). "We found that TTK is significantly overexpressed in BC cells and tissues, correlating with poor prognosis, which aligns with its established role as an oncogene in other cancers." (PMID 40269198, 2025). "High levels of TTK could prevent existing aneuploid cancer cells from further gaining or losing chromosomes, preventing cancer cells from compromising their viability." (PMID 38886738, 2024). "Notably, we identified different proteins that were previously associated with the adaptation to CIN in cancer, including the kinesin-like protein KIF2C/MCAK and the master SAC regulator MPS1/TTK." (PMID 38177531, 2024). "The ability of TTK to promote mitotic stability can be exploited for cancer treatment strategies." (PMID 38658569, 2024). "TTK was significantly upregulated in 18/33 cancer types versus normal tissues." (PMID 38195567, 2024). "We analyzed the TTK mRNA expression profile across various cancer types." (PMID 38195567, 2024). "Besides, the expression level of CDK1, CCNA2, CHEK1, KIF11, PLK1 and TTK was significantly elevated with cancer progression in LUAD." (PMID 38783288, 2024). "Recent evidence also indicates that TTK downregulation impedes cancer cell migration." (PMID 38195567, 2024). "However, TTK is overexpressed in many cancers, promoting tumor growth in glioblastoma, breast cancer and other cancers." (PMID 38195567, 2024). "Hence, we suggest that BAL0891 represents a first-in-class TTK/PLK1 inhibitor for the treatment of cancer patients." (PMID 39184047, 2024). "CCNA2, TTK, TOP2A, AURKA, AURKB and BUB1B are also closely associated with cancer." (PMID 39537209, 2024). "In addition, the expression level of CDK1, CHEK1, KIF11, PLK1 and TTK was significantly elevated with cancer progression in LUAD." (PMID 38783288, 2024). "In summary, TTK has emerged as a prospective biomarker and therapeutic target for cancer." (PMID 38195567, 2024). "Several TTK inhibitors have entered clinical trials for advanced cancer patients." (PMID 38410481, 2024). "Aberrant TTK overexpression has been noted across cancer types, implicating its oncogenic role." (PMID 38195567, 2024). "Taken together, these findings indicate aberrant TTK mRNA expression across many cancer types." (PMID 38195567, 2024). "The TIMER1.0 database was used to examine the TTK mRNA expression levels in pan-cancers." (PMID 36829176, 2023). "In contrast, genes dependent for only a subset of cell lines (e.g., TTK) might represent better therapeutic targets, as these could involve uniquely targetable dependencies for a subset of cancers, e.g., genes involved in “oncogene addiction”." (PMID 37141409, 2023). "In addition, overexpression of TTK is connected to cancer progression and poor prognosis in triple-positive breast cancer patients." (PMID 36829176, 2023).
cancer (continued). "Consequently, TTK has garnered substantial attention as a pivotal focus in cancer research, with TTK inhibitors undergoing escalating evaluation in clinical trials." (PMID 37894942, 2023). "TTK plays a regulatory role in cancer cell proliferation, cell cycle, and apoptosis." (PMID 37815894, 2023). "Therefore, to the best of our knowledge, this study is the first to report the probable cancer-driving role of the hsa-mir-124-3p miRNA with respect to TTK, BUB1B, NUSAP1, and ZWINT hub genes in OC." (PMID 37304238, 2023). "Besides its role in the cell cycle and SAC, TTK is overexpressed and correlates with advanced stages in several cancer types such as NSCLC, prostate, colon, and breast cancers." (PMID 36494865, 2022). "Retinoblastoma gene in cancer, another pathway associated with “Evasion of growth suppressors”, was also upregulated, with strong overexpression of pathways members leading to G1/S transition (CCNB1, CDK1) and mitotic spindle association (TTK)." (PMID 33917186, 2021). "We showed that fostamatinib (which can target PLK1 and other over-expressed serine/threonine kinases such as AURKA, MELK, NEK2, and TTK) is more active against cancer lines with more pronounced signatures of invasion (e.g., extracellular matrix organization/degradation)." (PMID 34680307, 2021). "A number of studies have shown that TTK has an important role in cancer, including HCC." (PMID 34257549, 2021). "Thus, we guess that TTK inhibitor in combination with antimitotic cancer drugs will enhance their efficacy and potentially overcome resistance." (PMID 34598710, 2021). "Selected by LASSO model, ANLN, TTK, AIM1L and person neoplasm cancer status might be candidate parameters associated with OS in HCC patients." (PMID 34130591, 2021). "In addition, inhibition of TTK expression can suppress the proliferation of cancer cells and result in significant survival benefits." (PMID 34988018, 2021). "The new research had speculated that TTK could regulate the proliferation and apoptosis of cancer cells via Akt-mTOR signaling pathway." (PMID 34187556, 2021). "A high TTK expression can easily be found in several types of human malignant tumors." (PMID 34988018, 2021). "Considering many TTK inhibitors are regarded as promising anti-cancer drugs, targeting TTK may be a novel strategy to treat OC, especially for the patients with advanced disease." (PMID 34516342, 2021). "TTK is tightly regulated during cancer development, however, the molecular mechanisms of TTK remains unknown." (PMID 32121246, 2020). "Interestingly, PBK, TTK, BAGE, and CT45A encode proteins termed cancer/testis antigens known to confer a selective advantage to tumor cells by promoting oncogenic processes or permitting evasion of tumor-suppressive mechanisms." (PMID 33239635, 2020). "However, the mechanistic details of how TTK-mediated signaling network supports cancer development is still a mystery." (PMID 32121246, 2020). "TTK is a mitotic checkpoint kinase that is highly expressed in several human cancers." (PMID 33187219, 2020). "To study whether NTS contributes TTK-mediated cancer growth and progression, we used exogenous NTS to reveal the change of cancer proliferation and migration augmented by TTK." (PMID 32121246, 2020). "TDRD6 and TTK are promising targets for cancer vaccines that could activate a number of immune cells, especially T cells and B cells." (PMID 32728493, 2020). "In addition, the expression level of TTK is significantly increased in various malignant tumors, and its high expression is closely related to a poor prognosis." (PMID 33148251, 2020). "Reduced in TTK level or activity in tumors can lead to a decrease of cell viability and division; thus, inhibition of TTK has been regard as an attractive target for anti-cancer drug development." (PMID 32121246, 2020). "In addition to promoting genomic instability and aneuploidy, TTK promotes cancer cell proliferation and invasion." (PMID 30206215, 2018).
cancer (continued). "In agreement with this hypothesis, high levels of TTK mRNA have been observed in multiple cancer types and been shown to be protective against aneuploidy." (PMID 28380042, 2017). "Moreover, LCM of malignant hepatocytes also revealed up-regulation of unique genes associated with cancer and signaling pathways, including two novel HCC-associated cancer testis antigen genes, NUF2 and TTK." (PMID 25141867, 2014). "From the subset of genes that were upregulated in HCC1954 cells compared to MCF10A cells, we chose shugoshin 1 (SGOL1) and TTK, based on their relevance and novelty, since the centrosome roles of these genes are not fully understood, especially in cancer models." (PMID 25278993, 2014). "One study has demonstrated that inactivation of TTK inhibited cancer cell growth in vitro, suggesting that targeting the gene might be an effective anticancer strategy." (PMID 24025726, 2013). "Since others have suggested that inhibition of mitotic checkpoint could have therapeutic potential in cancer treatment, we decided to focus on the potential deleterious effect of TTK silencing on TNBC cell lines." (PMID 23700430, 2013). "Thus, the TTK checkpoint may compensate for other defects in the mitotic spindle checkpoint through overexpression during mitosis, protecting cancer cells from genomic instability and preventing cell death." (PMID 39775836, 2025). "Similarly, the TIMER online database showed TTK upregulation in 21/33 cancers." (PMID 38195567, 2024). "Therefore, the authors speculated that TTK overexpression might activate SAC through phosphorylating the substrates to promote cancer cell growth." (PMID 37815894, 2023). "Taken together, we hypothesize TTK as a novel cancer-testis (CT)-related gene." (PMID 26418879, 2015). "Following the confirmation of EMT in EC, TTK, LY6K, and NOL4 have recently been reported as cancer-testis antigens with a bad prognosis, with TTK being particularly overexpressed in early-stage cancer." (PMID 41312167, 2025). "Dual inhibition of TTK and CLK has been found effectively inhibited tumor growth by affecting cancer cell mitosis and RNA splicing." (PMID 38723164, 2024). "Inhibiting the activity of BUB1B, TTK, and BUB3 can impede cancer cell proliferation, migration, and invasion." (PMID 38410481, 2024). "Differential expression analysis showed higher expression of MIIP, TTK, and EIF4A in tumors versus normal tissues across various cancers." (PMID 39015573, 2024). "IHC analysis revealed a significant increase in TTK and BUB1B expression in PDAC tissues compared to para-carcinoma tissues." (PMID 38711083, 2024). "Based on the statistical analyses of the PPI network of upregulated genes, AURKA, AURKB, TTK, MELK, and KIF20A were also involved in module 1, indicating their importance both in primary tumorigenesis and cancer progression." (PMID 37231064, 2023). "TTK has been described to activate AURKB through the phosphorylation of borealin during chromosome alignment and, consequently, treatment of cancer cells with TTKi leads to the inhibition of AURKB, as evidenced by a decrease in phosphor-histone H3 levels." (PMID 37443114, 2023). "This is the first comprehensive research that systemically investigates the clinical significance of TTK in PTC and its overexpression promoting the PTC progression through accelerating cancer cell growth and metastasis." (PMID 37815894, 2023). "In this regard, the Tyrosine Threonine Kinase (TTK) inhibitor CFI-402257 triggered aberrant chromosomal segregation and extensive aneuploidy in lung cancers and other cancers." (PMID 38031910, 2023).